SIK1 (salt inducible kinase 1)
Diseases named in the same sentence as SIK1 in open-access papers (continued):
Sharing a sentence is not in itself a finding about the gene and the disease.
tumor (45 papers, 2014 to 2025). "According to most reported research, SIK1 is considered a tumor suppressor, while SIK2 and SIK3 are often associated with tumor promotion." (PMID 39063214, 2024). "It has been reported to be associated with tumor malignancy suppression in a variety of cancers, of which SIK1 has been comprehensively reported." (PMID 37670972, 2023). "Despite the reported association of SIK1 with tumor malignancy suppression in various cancers, limited research has been conducted on its function in CRC." (PMID 37670972, 2023). "We showed that depletion of SIK1 causes inhibition of tumor cell growth, similar to the growth inhibition observed when EWSR1-WT1 is depleted." (PMID 35443736, 2022). "Taken together, suppression of SIK1 expression can rescue the tumor suppressive effects of BMI1 loss." (PMID 35346195, 2022). "In non-small cell lung cancer models driven by the KRAS[Gly12Asp] mutation, the tumour suppressive activity of LKB1 has been reported to be dependent on SIK1 and SIK3." (PMID 33861845, 2021). "Kaplan-Meier analysis of tumor samples revealed that high RNF2 expression with concurrent low SIK1 expression is associated with poor overall survival." (PMID 27911266, 2017). "In cancer biology SIK1 expression has been associated with a tumour suppressor function." (PMID 25384047, 2014). "SIK1 predominantly acts as a tumor suppressor by inhibiting epithelial‐mesenchymal transition and regulating gene expression to limit tumor progression." (PMID 39877288, 2025). "In this regard, it would be interesting to evaluate a combined therapy with dasatinib and recently identified DSRCT therapeutic targets NTRK3 or SIK1, which target the bulk tumor cells." (PMID 38177125, 2024). "SIK1, a serine/threonine kinase, regulates the cell cycle and gluconeogenesis and acts as a tumor suppressor; SPAG4 and JUNB regulate cell proliferation and differentiation." (PMID 39025980, 2024). "This study provides a first look at the tumor suppressive effects of SIK1 in CRC, complementing our previous work and providing new directions for CRC treatment by investigating this specific pathway in greater depth." (PMID 37670972, 2023). "Consistent with our in vitro findings, SIK1 depletion resulted in significantly fewer EdU+ cells in xenografts compared to controls, demonstrating a requirement for SIK1 in replicating tumor cell DNA in vivo." (PMID 35443736, 2022). "SIK1 had been proved to be a tumor suppressor to regulate OC progression, which was similar to the effect of circ_0078607 on OC progression and consistent with the previous research results." (PMID 34983607, 2022). "In previous studies, SIK1 has been found to have highly effective in preventing tumor formation and cancer progression." (PMID 34983607, 2022). "Previous studies have shown that SIK1 is a tumor suppressor and is regulated by transcription factors in some cancers." (PMID 35346195, 2022). "In our study, we discovered a significant positive correlation between circ_0078607 and SIK1 with low expression in OC tumor tissues." (PMID 34983607, 2022). "Our findings uncovered a tumor suppressor function of circEIF4G3 in GC through the regulation of δ-catenin protein stability and miR-4449/SIK1 axis." (PMID 35780119, 2022). "Then western blotting results from isolated tumor tissues showed that the protein levels of p-SIK1, SIK1 and E-Ca were upregulated, while VEGFA expression was downregulated in LKB1 overexpression group." (PMID 35912012, 2022). "In our study, we inhibited expression of SIK1 with siRNA and observed that proliferation and migration of SIK1-depleted OS cells significantly increased, which demonstrates that SIK1 plays a role in tumor suppression." (PMID 35346195, 2022). "The opposing nature of SIK1 in promoting or suppressing cell viability illustrates that the functions of SIK1 can be tumor cell-specific." (PMID 35443736, 2022).
tumor (continued). "Surprisingly, the correlation analysis results showed that there was a significant positive correlation between the expression of circ_0078607 and SIK1 in OC tumor tissues." (PMID 34983607, 2022). "Loss of Sik1 and Sik3 in the SIK subfamily, resulted in intensified tumor growth in in vivo models of KRAS-driven NSCLC." (PMID 34781949, 2021). "The tumour size and neutrophil infiltration in these models of SIK1/3 disruption were comparable to those seen when LKB1 was knocked out alongside the expression of KRAS[Gly12Asp]." (PMID 33861845, 2021). "In conclusion, the current study demonstrates that the intracellular miR-130b-3p affects the proliferation, migration and invasiveness of MB, which is mediated through targeting SIK1, and exosomal miR-130b-3p play a tumor suppressor role in MB tumorigenesis." (PMID 32483145, 2020). "Salt-inducible kinase 1 (SIK1) has been identified as an important factor in regulating sodium homeostasis and as a tumor repressor that participates in the progression of cancer cells." (PMID 32792949, 2020). "SIK1 is downregulated in several cancer types and has been shown to be a tumor suppressor by activating anoikis (anchorage-dependent cell death) to inhibit metastasis by suppressing metabolic reprogramming and epithelial to mesenchymal transitions." (PMID 31428057, 2019). "We found out that SIK1, an anti-metastatic protein, is a direct target of miR-223 and consequently is significantly reduced in miR-223-overexpressing tumor cells." (PMID 29296210, 2017). "Conversely, SIK1 levels were higher in non-tumor tissues (5.15 ± 0.41) than in HCC tissues (3.12 ± 0.29, P < 0.006)." (PMID 27911266, 2017). "The down-regulation of RNF2 expression in HCC cells significantly reduces tumor cell growth and metastasis, while the simultaneous down-regulation of both RNF2 and SIK1 restores tumor cell growth in vitro and in tumor xenograft models." (PMID 27911266, 2017). "Reduced sensitivity of Na+/K+‐ATPase to intracellular [Na+] via modulation of SIK1 signalling could be responsible for the increase in intracellular [Na+] seen in tumours." (PMID 36183245, 2023). "Ablation of LKB1 and its substrates SIK1/3 revealed their tumor suppressive effect in vivo." (PMID 38188023, 2023). "To explore whether SIK1 functions as a tumor suppressor in OS cells, we decreased SIK1 expression by transfecting three different siRNAs, siRNA #1, siRNA #2, and siRNA #3, into OS cells." (PMID 35346195, 2022). "We further investigated SIK1 gene expression in 36 paired tumor and adjacent non-tumor tissues and found that the expression of SIK1 was downregualted in GC and positively associated with that of circEIF4G3." (PMID 35780119, 2022). "Besides, SIK1 expression also was lower in OC tumor tissues than that in adjacent normal tissues at the mRNA level and protein level." (PMID 34983607, 2022). "The tumor suppressor SIK1 was identified as the direct target gene of BMI1 in OS cells." (PMID 35346195, 2022). "Previous studies identified SIK1 as a potent tumor suppressor." (PMID 35346195, 2022). "Moreover, SIK1 expression was also increased in mouse tumor tissues in circEIF4G3 overexpressing group." (PMID 35780119, 2022). "Previous research has shown that SIK1 is a tumor suppressor in many cancers." (PMID 32483145, 2020). "Interestingly, in the current study, we identified SIK1 as a tumor-promoting protein, as it can induce tumor cell proliferation, invasion and metastasis in vivo/vitro." (PMID 32483145, 2020).
tumor (continued). "Importantly, The knockdown of RNF2 expression through RNA interference significantly reduced the growth of xenograft tumors, whereas knocking down both RNF2 and SIK1 expression reversed tumor growth to the level of the control group." (PMID 27911266, 2017). "In addition, our data suggest that the anti-metastatic SIK1 is a target of miR-223 and over-expression of miR-223 contributes to a more aggressive tumor phenotype." (PMID 29296210, 2017). "Expression of conditionally active SIK1 in LKB1 mutant A549 cell lines suppressed invasion and pulmonary metastasis, thus implicating an important role for the SIK1 in progression and metastasis of LKB1-deficient tumours." (PMID 26196184, 2015). "In addition, SIK1 knockdown can increase metastasis by increasing Epithelial-Mesenchymal Transition (EMT) in CRC cells 8, 9, suggesting that SIK1 may be a tumor suppressor gene." (PMID 37670972, 2023). "In addition, we found an unreported role of SIK1 in promoting MB tumor growth and an SIK1 inhibitor could inhibit MB cell proliferation." (PMID 32483145, 2020). "Thus, we examined SIK1 protein expression in available tumour biopsies by immunoblotting." (PMID 29296210, 2017). "Protein and gene expression analyses in patient samples revealed that SIK1, SIK2, SIK3, and PARD3 were all highly expressed in tumor tissues compared to adjacent normal tissues (p < 0.01)." (PMID 39063214, 2024). "In support of this, SIK1 and SIK3 were shown to control IL-6 production in tumor cells and IL-6 and IL-1β production in Raw264.7 macrophages." (PMID 37140993, 2023). "We further showed that silencing SIK1 leads to cessation of DNA replication in DSRCT cells and inhibition of tumor growth in vivo." (PMID 35443736, 2022). "Authors concluded that SIK1 and SIK3 were highly responsible for STK11 tumor suppressing functions and can therefore be important targets to mediate these pathways for therapeutic reasons." (PMID 34781949, 2021). "In these studies, lentivirus was used to deliver Cre-recombinase to drive the expression of KRAS[Gly12Asp] whilst simultaneously delivering CRISPR guides to disrupt SIK1 and SIK3 expression, which accelerated tumour growth." (PMID 33861845, 2021). "We examined several of these tumor suppressors by qRT-PCR including p21, CHOP, SIK1, MXD1 and several others, each of which showed dramatic increases after corin treatment vs. MS-275 treatment, confirming the microarray data." (PMID 29302039, 2018). "We previously reported that downregulation of SIK1 markedly promotes HCC cells proliferation, migration, invasion, as well as EMT in vitro and increases tumor growth and metastasis in the mouse xenograft model." (PMID 27911266, 2017). "Furthermore, when tumour biopsies were assessed for protein expression by immunohistochemistry, SIK1 was found weakly expressed in high miR-223 cases, suggesting that high levels of miR-223 could function as oncomir by SIK1 repression." (PMID 29296210, 2017). "To further investigate the expression patterns of RNF2 and SIK1 in HCC, we randomly examined six pairs of human HCC samples and matched non-tumor tissues." (PMID 27911266, 2017). "Furthermore, SIK1 modulates metastasis by regulating the epithelial-mesenchymal transition (EMT) process, which is an essential pathway for tumor cells to gain mobility and metastasize." (PMID 36731029, 2023). "In our cohort, the expression of SIK1 did not significantly differ between tumor and adjacent non-tumor tissue." (PMID 37670972, 2023).
tumor (continued). "Consistent with the in vitro studies, SIK1 depletion resulted in a significant inhibition of tumor growth of both JN- and BER-shSIK1 xenografts but not in the untreated (except JN-shSIK1) nor in control xenografts." (PMID 35443736, 2022). "Although SIK1 has been shown to be a tumor suppressor gene in multiple tumor types, no one has so far validated its role in OS cells." (PMID 35346195, 2022). "In OC tumor tissues, SIK1 mRNA expression was discovered to be negatively correlated with miR-32-5p expression." (PMID 34983607, 2022). "Among these target genes, we focused on a tumor suppressor, SIK1, and sought to determine whether BMI1 directly regulates SIK1 transcription." (PMID 35346195, 2022). "Next, we analyzed SIK1 expression levels in 25 MB tumor tissue specimens and 15 nontumor tissues through RT-qPCR, and the results showed that SIK1 mRNA expression levels were remarkably upregulated in the MB tissue specimens compared with the nontumor tissues." (PMID 32483145, 2020). "SIK1 expression was significantly lower in hepatocellular carcinoma, compared to normal liver biopsies, and its overexpression in cancer cells suppressed the expression of EMT markers, tumour growth and metastases in a xenograft tumour model." (PMID 31819138, 2019). "In the absence of LKB1, SIK1/3 activity is reduced, but promotes tumor growth." (PMID 32516941, 2020). "On the contrary, our findings confirmed that restoration of SIK1 induced by RNF2 depletion could inhibit cell growth and induce cell apoptosis in HCC cells, and that SIK1 siRNA can counteract the inhibitory effect of RNF2 lost on tumor growth." (PMID 27911266, 2017). "This notion is further supported by recent CRISPR/Cas9-mediated gene editing studies revealing that knock-outs of SIK1 and SIK3, but not of other AMPK family members, increased tumor growth in a mouse model of oncogenic KRAS-driven lung adenocarcinoma." (PMID 34142658, 2021).
cancer (27 papers, 2014 to 2025). A tumor composed of atypical neoplastic, often pleomorphic cells that invade other tissues. "With the development of research, more and more studies have confirmed that SIK1 expression is also associated with the progression of many cancers, including hepatocellular carcinoma, pancreatic cancer and colorectal cancer." (PMID 34983607, 2022). "In other cancer types, the loss of SIK1 expression promoted the expression of EMT markers, as well as invasive capacities both in vitro and in vivo." (PMID 31819138, 2019). "Recent studies have shown that reduced levels of SIK1 are associated with poor outcome in cancers, and that this involves an invasive cellular phenotype with increased metastatic potential." (PMID 25384047, 2014). "We have revealed that BMI1 exerts its cancer-promoting effect by mediating transcriptional repression of SIK1, which provides a potential therapeutic target for OS." (PMID 35346195, 2022). "Recently, NaV1.5 was identified as importantly promoting the epithelial-to-mesenchymal transition (EMT) and cancer cell invasiveness through the regulation of the salt-inducible kinase 1 (SIK1)." (PMID 33817575, 2021). "Recently, several MicroRNAs have been reported to target SIK1 in promoting cancer cell proliferation or migration." (PMID 32788639, 2020). "Our results further support the potential of using FACNI and SIK1 as prognosis marker and provide insight in broadening its application in other cancer types." (PMID 30729033, 2019). "Intriguingly, some of the possible miR-141 targets are associated with cancer metastasis e.g. DLC1, insulin receptor substrate 2 (IRS2) and salt-inducible kinase 1 (SIK1)." (PMID 28095864, 2017). "The specific mechanism is that EMT can promote the transformation of cancer cells into cancer stem cells (CSCs) and acquire drug resistance 22, 25, and we found that SIK1 can inhibit oxaliplatin resistance in oxaliplatin drug experiments and in vivo experiments." (PMID 37670972, 2023). "Furthermore, knocking down SIK1 expression induces NaV1.5 expression and is correlated with the increase of cancer cell invasiveness." (PMID 31819138, 2019). "Several members of the matrix metalloproteinase (MMP) family are shown to trigger cancer cell migration, so we hypothesized that the inhibitory effect of SIK1 on migration may involve regulation of MMPs." (PMID 25384047, 2014). "As a direct downstream gene of LKB1, under normal circumstances, SIK1 and SIK2 are mainly involved in body metabolism, while SIK3 promotes the occurrence of cancer by interacting with the mTOR complex." (PMID 39063214, 2024). "The three SIK isoforms (SIK1, SIK2, and SIK3) are serine/threonine protein kinases of the AMP-activated kinases family known to regulate metabolism, cancer, melanocytes, and bone formation." (PMID 36246922, 2022). "It should be noted that SIK1 is a transcriptional target induced by cAMP-CREB signaling and it was upregulated in LKB1-null cancer cells." (PMID 34142658, 2021). "SIK1 downregulation by dnCRTC was only observed in LKB1-null, but not LKB1-wt cancer cells in this study, which is unlikely to have functional consequences as SIK1 kinase is impaired in LKB1-null cancer cells." (PMID 34142658, 2021). "Since SIK3 is homologous to SIK1 and SIK2, further studies were conducted to determine whether a broader requirement exists for SIKs in cancer." (PMID 30723708, 2019). "Besides, whether the SIK1/PI3K/AKT and CCL20/CCR6 signaling pathways for miR-183-5p are specific in HCC and whether the axis has an effect on angiogenesis in other cancers remain questions that need to be explored." (PMID 40115013, 2025).
cancer (continued). "The loss of SIK1 expression in epithelial-like phenotype MCF-7 cells promoted the expression of SNAI1, but did not significantly modulate its expression in MDA-MB-231 cancer cells already largely engaged in a mesenchymal phenotype." (PMID 31819138, 2019). "However, the molecular mechanism(s) regulated by SIK1 in cancer cells is not well explored." (PMID 25384047, 2014). "The main research direction of SIK1 regulating the TGF-β signaling pathway is further in non-N-cadherin diseases 12, 13, but there is a lack of research in cancer, and even the specific mechanism has not been determined and still needs to be researched in depth." (PMID 37670972, 2023).
infection (6 papers, 2019 to 2025). The state of being infected such as from the introduction of a foreign agent such as serum, vaccine, antigenic substance or organism. "Immunoblot analysis showed that overexpression of SIK1 via ad-SIK1 infection increased SIK1 protein levels in C28/I2 cells under IL-1β treatment for 24 h." (PMID 40059873, 2025). "To further elucidate the role of SIK1 in AA-induced HK2 cells injury, we constructed cell lines that stably up-regulated SIK1 by lentivirus infection of HK2 cells." (PMID 33588892, 2021). "Notably, additional infection of mouse hepatocytes with ad-SIK1 virus markedly reversed the effects of HG-9-91-01 treatment on the transcription of various molecules." (PMID 33013689, 2020). "Furthermore, Oil Red O staining also confirmed the trends of lipid metabolism changes upon SIK1 inhibition and ad-SIK1 infection in mouse primary liver cells, corroborating the qRT-PCR and immunoblotting data." (PMID 33013689, 2020). "They found increased expression of genes from the box C/D snoRNO complex (NOP1, NOP58, and SIK1), which coincides with our findings, as proteins from the box C/D snoRNO complex were in greater abundance in P1, confirming involvement of ribosome biogenesis during infection." (PMID 31293987, 2019). "Otherwise, SIK1 inhibitors were shown to inhibit TLR-induced inflammation, which may lead to adverse events such as infection." (PMID 39959414, 2025).